LGR5 (leucine rich repeat containing G protein-coupled receptor 5)
Diseases named in the same sentence as LGR5 in open-access papers (continued):
Sharing a sentence is not in itself a finding about the gene and the disease.
tumor (continued). "Together, these findings cast bile acids as potent, pleiotropic oncometabolites that can influence both Lgr5+ and Lgr5− populations, expanding the potential tumour-initiating pool." (PMID 33673710, 2021). "They identified both ATOH1 and LGR5 double positive tumor cells as well as LGR5 single positive tumor cells, suggesting that colitic tumors are mosaic and consisted of a heterogenous population of tumor stem cell." (PMID 33541282, 2021). "The influence of stem cells and the result of their elimination in tumor tissue was also demonstrated with the Lgr5-eGFP-DTR transgenic mouse model." (PMID 33671641, 2021). "Measurements of CXCL16 and CXCL17 strengthen the prognostic value of LGR5 by detecting high number of aggressive tumor cells and/or tumor growth promoting cells in the tumor cell microenvironment." (PMID 35008827, 2021). "High expression of LGR5 was correlated with more depth of tumor invasion, lymph node (LN) metastasis, advanced cTNM stage and mesorectal fascia (MRF) involvement." (PMID 34582650, 2021). "They showed that cancer buds expressed various amounts of LGR5 and PD-L1 and suggested that patients having PD-L1-negative tumour buds should receive different treatment, affecting the CSC marker LGR5." (PMID 34884696, 2021). "We then analyzed the tumor cellular composition from different therapy groups by FACS, and found Lgr5+ cells were reduced according to the tumor volumes." (PMID 34345013, 2021). "Tumor budding cells express high levels of the cancer stem cell markers LGR5, ALDH1A, CD44, and always escape immune surveillance." (PMID 34771607, 2021). "Lgr5+ stem cells were shown to be required for the formation of normal tissue organoids as well as tumor organoids." (PMID 33671641, 2021). "These lineage tracing results showed that Lgr5+ cells contribute to tumor formation and metastasis, which processes were remarkably abrogated by miR-22 deficiency." (PMID 34345013, 2021). "A significant increase in expression of LGR5 (p: 0.003) gene was found in G1 stage tumor tissues (group 8) compared to the control group." (PMID 34452555, 2021). "LGR5-positive cells have been shown to be the cancer stem cells responsible for tumor growth and metastasis in CRCs15,16." (PMID 34493772, 2021). "Together, these results showed that pair-wise genetic perturbation of HDGF and LGR5 with the addition of MAPKi efficiently disrupted the formation of tumor spheroids in the 3D growth environment." (PMID 34106558, 2021). "Consistent with this, nedd4L has been reported as a tumor suppressor by regulating several protein targets, such as LGR5 and DVL2." (PMID 34769140, 2021). "Such lesions are not typically observed upon sole deletion of Apc in other putative tumour-initiating cell populations, including Lgr5+ ISCs." (PMID 33673710, 2021). "To analyze if DNA hypomethylation suppresses intestinal tumorigenesis in Uhrf1ki/ki/ApcMin/+ mice by affecting tumor stem cells, we examined the levels of intestinal stem-cell marker genes Lgr5, Ascl2, and Sox9 by qRT-PCR." (PMID 33947834, 2021). "Lgr5+ cells have been shown to be representative of the cell of origin of intestinal tumourigenesis and have tumour-initiating potential." (PMID 34680897, 2021). "These cells upregulated stem cell markers, like Lgr5 and Ascl2, and recapitulated the Wnt activity heterogeneity upon tumor growth." (PMID 33671641, 2021). "They generated Lgr5-eGFP (L) patient tumor organoids that expressed TagRFP fused to the endogenous Ki67 protein (K)." (PMID 33671641, 2021). "To further evaluate the stem cell property of Lgr5+ cells from induced tumor tissues as well as the function of miR-22 within these cells, we analyzed their self-renewal and in vitro expansion ability." (PMID 34345013, 2021). "Instead, tumours remained in a state of stasis while Lgr5− populations mobilized to sustain growth, albeit less efficiently than Lgr5+ counterparts." (PMID 33673710, 2021).
tumor (continued). "It is well-known that LGR5 is one of the best prognostic biomarkers for drug resistance or tumor relapse for many types of cancers and has been usually reported as an activator of the Wnt/β-catenin signaling pathway." (PMID 34106558, 2021). "They found that both Lgr5+ and Lgr5− cells escaped from the primary tumor, but that a significant majority were Lgr5− cells." (PMID 33671641, 2021). "For instance, hyperactivation of the WNT signaling pathway turns intestinal LGR5+ cells into tumor-initiating cancer stem cells (CSCs), but the cells that disseminate from the primary tumor and seed liver metastasis in mouse models are predominantly LGR5–." (PMID 34100888, 2021). "Surprisingly, lineage tracing of emergent tumours in this model showed that they harbour a reduced number of Lgr5+ cells but an increased proportion of Bmi1+ cells." (PMID 33673710, 2021). "Particularly, LGR5 expression levels significantly correlated with depth of tumor invasion (p=0.002)." (PMID 34582650, 2021). "Treatment of tumor organoids with sorafenib significantly increased the percentage of LGR5-positive cells in the population." (PMID 32327656, 2020). "In Gastric adenocarcinoma tissues, a positive relationship between CD133/Lgr5 expression and VC formations, microvessel density, tumor grade, lymph node metastasis and TNM staging has been shown." (PMID 32296643, 2020). "Of note, the overall H-score of LGR5 expression in AM tumor tissues was about fourfold higher than that in normal control and OCs." (PMID 32382005, 2020). "In accordance with that, both Lgr5 and Lgr6 showed the highest mRNA expression levels in this tumour type in dogs (present results) and humans." (PMID 32397255, 2020). "Among them, LGR mRNA and Lgr5 protein expression pattern is dynamic, with respect to cellular localization (nuclear vs. cytoplasmic/membranous) and to tumor pathologic attributes (anatomical epicenter, histotype and molecular subtypes)." (PMID 32894084, 2020). "We showed that tumor growth is significantly attenuated upon administration of anti-LGR5-ADC using a human-in-mouse PDX model expressing elevated levels of LGR5." (PMID 32522170, 2020). "We knocked out ABCG1 in AT2 cells, then cocultured with Lgr5 cells and found that the capacities of colony formation and tumor initiation of AT2 cells were suppressed." (PMID 32157214, 2020). "Our DCIS TMA-derived data suggested a role for LGR5 in tumor initiation of BC with less favorable outcome." (PMID 32522170, 2020). "LGR5 expression correlated with small tumor size, lower grade, lymph node negativity, and ER-positivity." (PMID 32522170, 2020). "The relative abundance of LGR5 cells in the tumors is significantly higher as compared with those in the tumor-surrounding tissues or as detected in CCl4-injured livers." (PMID 32327656, 2020). "Given that LGR5 appears to have an important role in tumor initiation and progression of ER− BC, we explored the ability to target LGR5 therapeutically." (PMID 32522170, 2020). "Meanwhile, purified LGR5+ epithelial cells displayed enhanced capacities to form 3D-spheroid in vitro and to generate tumor-like structures in vivo." (PMID 32382005, 2020). "Time-course analysis of Lgr5 expression in tumor organoids by analysis of GFP intensity showed that as the tumor organoids grew, CSC activation did not change." (PMID 33087710, 2020). "This suggests the susceptibility to treatment observed here and in other studies is a conserved feature of LGR5+ cells in both normal tissue and tumours." (PMID 31906589, 2020). "We found that LGR5 expression is significantly elevated in tumor tissues compared with the paired tumor-free liver tissues, and also in some subpopulations of patients with specific etiologies of HCC." (PMID 32327656, 2020). "In normal tissues and tumours, it appears that cellular plasticity within intestinal cell populations allows LGR5- progenitors to revert back into a stem-like state and reconstitute the ablated LGR5+ stem cells." (PMID 31906589, 2020).
tumor (continued). "To define the potential for therapeutic targeting, we have performed LGR5 lineage ablation in organoids in vitro and in the tumor-bearing mouse model." (PMID 32327656, 2020). "Here, we found that both C-B and C-I inhibit colonosphere formation and the expression of all three CSCs markers DCLK1, LGR5, and CD44v, both in cell culture and in vivo in mouse tumor xenograft models." (PMID 31992775, 2020). "LGR5 negatively correlated to tumor size (P = 0.001), nodal metastasis (P = 0.002), Nottingham histological grade (NHG) (P = 0.047) and ER (P = 0.001)." (PMID 32522170, 2020). "This was recently demonstrated via antibody–drug conjugates targeting Lgr5+ cells, which resulted in a reduction in tumor size, extended patient survival, and prevention of cancer recurrence." (PMID 31947553, 2020). "In vivo studies performed by other groups and confirmed by us, have shown that LGR5+ ER− BC cells bear an enhanced tumor-initiating capacity." (PMID 32522170, 2020). "Lastly, we performed in vitro and in vivo studies in various mouse models of BC to further substantiate a role for LGR5 in tumor initiation and solidify LGR5 as a valid therapeutic target for TNBC." (PMID 32522170, 2020). "Using absolute tumor size as a measure, DT-mediated depletion of the LGR5+ compartment impaired tumor growth." (PMID 32327656, 2020). "Specifically, targeted ablation of the Lgr5 stem cell population in cancerous tissues revealed that it is dispensable for primary tumor maintenance." (PMID 33225975, 2020). "Participation of CRCSCs in tumor neovascularization has been demonstrated in tumor tissues by CD31/CD133/Lgr5 co-expression." (PMID 32296643, 2020). "In conclusion, our work shows that NEDD4 and NEDD4L are crypt‐expressing tumour suppressors by targeting the RSPO receptor LGR5 and DVL2 for degradation." (PMID 31867777, 2020). "The decreased LGR5, β-catenin, mTOR, and IL-6 levels, and increased miR-142-3p level in tumor samples collected from mice that received MSI-N1014, support our proposed anti-CRC mechanism of action." (PMID 32560222, 2020). "DT treatment inhibited the growth of tumor organoids in an effect that showed close correlation as to the effects on the numbers of LGR5–GFP+ cells." (PMID 32327656, 2020). "By knocking out α6, β4, or both in AT2 cells and then coculturing with Lgr5 cells, we found that colony formation and tumor formation capacities were suppressed." (PMID 32157214, 2020). "To establish LGR5 as a valuable therapeutic target, we assessed and substantiated a role for LGR5+ cells in tumor initiation." (PMID 32522170, 2020). "Our meta-analysis reveals that AXIN2 is consistently expressed at a higher level in tumor relative to normal tissue, and so is LGR5, indicating as expected increased Wnt/β-catenin signaling activity and increased stem cell identity of tumor tissue." (PMID 32403323, 2020). "Further analysis showed that the percentage of cells co-expressing LGR5 and ALDH1, LGR5 and OCT4, and LGR5 and ZEB1 in tumor-like structures formed by LGR5+ AM epithelial cells was significantly higher than that in those formed by parental AM epithelial cells." (PMID 32382005, 2020). "Previous reports have revealed a cancer stem cell (CSC) population within ES tumours, identifiable by expression of the cell surface receptor leucine-rich repeat-containing G-protein coupled receptor 5 (LGR5)." (PMID 31722230, 2020). "The expression of a subset of genes is associated with CSCs, including markers such as Lgr5, CD133, and CD44, as well as other genes involved in the acquisition of stemness traits in tumor cells, such as transcription factors Nanog, Stat‐3, and c‐Myc." (PMID 31788944, 2020). "The LGR5 expression levels in the tumor cells show substantial variation, but are substantially and significantly higher compared with that in injured liver." (PMID 32327656, 2020). "Conversely, the tumor-suppressive function of Lgr5 has also been described on the basis of several clinical and experimental studies." (PMID 31901081, 2020).
tumor (continued). "Here we further substantiated a role for LGR5 in tumor initiation in TNBC by utilizing a lineage-tracing experiment in an autochthonous mouse model with high expression of LGR5 in hyperplastic ER− TNBC." (PMID 32522170, 2020). "Tumor samples from the MSI-N1014 group showed markedly reduced expressions of LGR5, β-catenin, IL-6, and mTOR, but increased expression of the tumor suppressor, miR-142-3p, according to qRT-PCR analysis." (PMID 32560222, 2020). "By immunofluorescence staining of LGR5, the tumour cells in the lung tended to have large patchy staining in the cytoplasm compared to small dotty staining in the liver." (PMID 32081957, 2020). "C-B and C-I downregulated the expression of DCLK1, CD44 and LGR5 in HCT116 tumor samples relative to the vehicle control." (PMID 31992775, 2020). "This furthermore supports a role for LGR5, not only in tumor-initiation, but also for metastatic progression." (PMID 32522170, 2020). "All hyperplastic foci within the tamoxifen-induced triple-transgenic mice exhibited red fluorescence, denoting the tumor-initiating capacity of Lgr5+ cells." (PMID 32522170, 2020). "A similar conclusion of a high level of Lgr5 is an unfavorable factor with a shorter OS and disease-free survival (independent from tumor size) was also given in many other studies." (PMID 32671503, 2020). "LGR5 has been suggested as a cancer stem cell marker, and targeting LGR5+ cells with anti-LGR5 antibody–drug conjugates suppressed tumor growth and metastasis in a preclinical model." (PMID 33291655, 2020). "Meanwhile, in the tumor-like structures formed by transplanted parental and LGR5+ AM epithelial cells, about 60% of cells co-expressed LGR5 and proliferating cell nuclear antigen (PCNA)." (PMID 32382005, 2020). "The number of LGR5+ cells as well as the cytoplasmic staining intensity were variable across the primary tumour specimens." (PMID 31906589, 2020). "Lgr5(+) cells are seen at the crypt base in IM, and the expression becomes more marked in carcinoma in its luminal surface, tumor center and the invasion front type." (PMID 32894084, 2020). "Selective ablation of Lgr5+ cells induces tumor regression in organoids, while a re-emergence of Lgr5+ cells was observed to drive tumor re-growth." (PMID 31947553, 2020). "To investigate the importance of LGR5 in colony-formation that evaluates tumor-initiating capacity, we performed an in vitro sphere assay using MDA-ctrl and MDA-LGR5KD cells." (PMID 32522170, 2020). "As expected, LGR5+ cells display a stronger capacity for tumor initiation as compared with LGR5− cells (LGR5+ vs. LGR5−: 33.3% vs. 11.1%)." (PMID 32327656, 2020). "Of note, LGR5+ cells isolated from 5-FU-treated tumors retained the ability of organoid and tumor initiation." (PMID 32327656, 2020). "In their totality, our data indicate the potential role of LGR5 both as a prognostic tool to determine malignant DCIS lesions alongside the value of utilizing LGR5 to stratify ER+ and ER− BC tumor grade and recurrence." (PMID 32522170, 2020). "Lgr5 mRNA expression was observed in all the HF tumours, with the highest levels in TB cases, with an average fold change increase of 14 compared with normal skin." (PMID 32397255, 2020). "In intestinal adenoma as well as malignant carcinoma, LGR5 cells account consistently for a ratio of 5–10% of tumor cells and fuel tumor growth." (PMID 32327656, 2020). "Treatment with either sorafenib or 5-FU to mice-bearing allograft tumors, formed by engrafting tumor organoids, substantially increased the fraction of the LGR5–GFP+ cells in the tumors." (PMID 32327656, 2020). "LGR5 is highly expressed in colorectal tumors and marks colon cancer stem cells that drive tumor growth and metastasis." (PMID 33081383, 2020). "Colony assays and xenograft experiments substantiated a role for LGR5 in ER− tumor initiation and subsequent growth, which was further validated by lineage-tracing experiments in ER− /triple-negative BC mouse models." (PMID 32522170, 2020).